CD4 (CD4 molecule)
Diseases named in the same sentence as CD4 in open-access papers (continued):
Sharing a sentence is not in itself a finding about the gene and the disease.
anemia (continued). "The protective effect of multivitamin supplements on anaemia and severe anaemia was not modified by birth weight, baseline HIV status, sex of child and maternal CD4+cell counts." (PMID 23948440, 2013). "Adjusting for baseline CD4 count, HIV symptoms, BMI or anemia yielded similar results and did not change this finding." (PMID 22254084, 2011). "Without such data, we are unable to report on how improved CD4 count and viral load or certain ART regimens may have impacted trends of anaemia over time." (PMID 40396424, 2025). "WHO clinical staging III/IV, CD4 count below the threshold level, CPT non-user, poor adherence, and before test and treat strategies (pre-ART) were found to be the main predictors of anemia." (PMID 33785009, 2021). "However, the time to gain 100 CD4 cells/L was 43% slower (p < 0.05) and the frailty was higher at month 12 for PLWHA with the baseline or sustained macrocytic vs. no anemia." (PMID 30935133, 2019). "This was also often the approach used by patients who were monitoring indicators that they themselves could not measure, such as cholesterol, blood count values in anemia, HIV viral load levels, and CD4 counts." (PMID 26290186, 2015). "However, stool consistency, CD4+ count, HARRT, HARRT duration (year),WBC and platelet count, nutritional status, anaemia, drinking alcohol, WHO stage for HIV were not statistically significant risk factors for VRE (P > 0.05)." (PMID 24555580, 2014). "Risk of TB was higher in those with markers of TB infection (positive TST but no treatment of LTBI, and TB treatment in the past); those with inadequate control of HIV infection (low CD4 count; non-use of HAART), those with poor general health (low BMI; anemia) and illiterate." (PMID 23675515, 2013).
Obesity (380 papers, 2010 to 2026). Accumulation of substantial excess body fat. "MR and colocalization evidence was observed for 1630 genes associated with one or more obesity-related traits, mainly expressed in CD4+ naive/central memory T cells and enriched in antigen processing and presentation pathways." (PMID 42117609, 2026). "Among those with CD4+ T cell counts < 500 cells/μL, the inverse association between obesity and LTBI was even more marked (adjusted OR = 0.20, 95% CI: 0.05–0.83, p = 0.027)." (PMID 41305316, 2025). "In the current study, Individuals with a low CD4 count at baseline have a significantly higher risk of being overweight/obesity compared to those with a higher CD4 count." (PMID 40920752, 2025). "The development of overweight/obesity was positively associated with being married, increasing waist circumference, and having a CD4 count below 200 cells/μl, while older age appeared to have a protective effect." (PMID 40920752, 2025). "In our sample, CD4 memory T-cells (Tcm) were associated with Black race, African ancestry, obesity, late stage and survival over 2 years." (PMID 41224793, 2025). "Being married, low CD4 count, and increased waist circumference were positively associated with overweight/obesity, while age was inversely associated." (PMID 40920752, 2025). "While obesity-induced expansion of MDSCs was observed in both sexes, male OD mice were more susceptible to the dysregulation of CD4+ and CD8+ T cells." (PMID 39125804, 2024). "In CD4+-T-cell-specific KLF10 knockout mice, a predisposition to obesity, insulin resistance, and fatty liver was observed, attributed to impaired CD4+ Treg mobilization to liver and adipose tissues and reduced TGF-β3 release." (PMID 38279278, 2024). "Reported findings indicate that dysglycemia, characterized by elevated levels of IR in human obesity, is associated with the recirculation of partially dysfunctional polyclonal PD-1+CD4 Tconv from VAT to PB." (PMID 38380252, 2024). "Older age, higher CD4 cell counts, and insufficient physical activity were associated with overweight and obesity." (PMID 39735593, 2024). "We also found that older age, higher CD4 cell counts, and insufficient physical activity were significantly associated with overweight and obesity among PLWH on ART." (PMID 39735593, 2024). "Older, higher CD4 cell counts, and insufficient physical activity were significantly associated with overweight and obesity among PLWH on ART." (PMID 39735593, 2024). "Recent research suggests that there is a shift in balance from anti-inflammatory CD4+ Treg cells towards pro-inflammatory CD4+ Th17 lymphocytes in obese individuals, which are involved in obesity-related pathologies and associated with a high degree of IR." (PMID 38397726, 2024). "All together these data indicate that dysglycemia in human obesity is associated with increased recirculation of PD-1+CD4 Tconv cells with unrestricted TCRβ repertoire from VAT to PB." (PMID 38380252, 2024). "Currently, there is limited understanding of tissue-specific characteristics of VAT-derived CD4 T cells and their role in causing dysglycemia in human obesity." (PMID 38380252, 2024). "In animals, curcumin supplementation was shown to reduce obesity and glucose intolerance, fibrosis, and intrahepatic accumulation of CD4+ cells in association with NAFLD." (PMID 38170037, 2023). "Our findings are also consistent with analyses of other cohorts in SSA that reported male sex, old age, low nadir CD4 count, and obesity as risk factors for hypertension." (PMID 36800379, 2023). "Another possibility is that in patients with obesity, insulin resistance leads to an abnormal T-cell response to pathogens and a deficiency in CD4+ T and CD8+ T lymphocytes, which is essential for their adaptive immune response against infection." (PMID 37374943, 2023).
Obesity (continued). "Pregnancy complicated by obesity is associated with adverse triggered gestational and neonatal outcomes, with reductions in the subtypes of CD4+ T-lymphocytes representing the modulators of inflammation." (PMID 36768983, 2023). "A possible link between SPP1/OPN and obesity has been reported as CD153+PD-1+CD4+ T cells cause inflammation of visceral adipose tissue and insulin resistance under HFD conditions or in obesity by secreting SPP1/OPN." (PMID 37670786, 2023). "Altogether, these findings demonstrate that T cell-specific leptin signaling is required for some of the changes in CD4+ T cell metabolism and function observed in obesity but has minimal effects on obesity-associated systemic metabolism." (PMID 37276236, 2023). "Adolescents who had infections were excluded from this study, so the increase in CD4 and IL-6 levels seems to be associated with obesity." (PMID 37859769, 2023). "A recent study showed that gastric bypass was shown to temporarily reverse obesity-associated accelerated CD4+ T cell aging." (PMID 37266430, 2023). "It has been implicated that CD4+ T cells, especially Tregs, play critical roles in the regulation of IR, adipose inflammation and obesity." (PMID 35912096, 2022). "In this study, we showed the reduced number and anti-tumor immune dysfunction of CD4+ T cells in the obesity-associated TIME of MC38 cells." (PMID 36611881, 2022). "Regarding BMI, obesity was associated with a lower percentage of IL‐10+FoxP3+CD4+ T‐cells only in patients with severe AA when compared to other patients and the control group." (PMID 35734271, 2022). "Although preliminary, our findings showed that obesity favors the expansion of circulating Th17‐like cells and hybrid Th2/Th17 phenotype associated with AA severity, together with damage to regulatory CD4+ T cell subsets and Br1 cells." (PMID 35734271, 2022). "Collectively, these findings suggest that decreased “helper” function due to CD4+ T cell reduction and exhaustion in obesity-associated TIME led to decreased cytotoxic activity of CD8+ T cells." (PMID 36611881, 2022). "Females, older age, longer duration on ART, CD4 + T-cell count and presence of NCDs were found to be associated with overweight and obesity (p < 0.05)." (PMID 36167612, 2022). "It is possible that immune imbalance associated with obesity and elevated leptin levels favor the expansion of different CD4+ T cell subsets associated with AA severity." (PMID 35734271, 2022). "This suggests that CD107a expression of CD8+ T cells, which is reduced in HFD-fed mice, was caused by the reduced number and dysfunction of CD4+ cells due to HFD-induced obesity." (PMID 36611881, 2022). "In conclusion, we showed that the reduction and anti-tumor immune dysfunction of CD4+ T cells contribute to the acceleration of tumor growth in the obesity-associated TIME in tumor-bearing 45% HFD-fed mice." (PMID 36611881, 2022). "Adipose tissue infiltration by macrophages, CD8+T cells, and CD4+T cells is associated with obesity in mice and humans." (PMID 36552029, 2022). "This apparent discrepancy between mortality rate and CD4 T cell restoration exemplified the diverse impacts of obesity which is associated simultaneously with positive and negative effects." (PMID 34220817, 2021). "High-risk obesity cases, N = 14 showed lower vaccine-specific-CD3+ CD4+ T-cell response compared to low-risk obesity patients, N = 17, p = 0.02." (PMID 33431890, 2021). "Surprisingly, the central players in adaptive and innate immune responses, such as CD4+ T and NK cells, are strongly associated with obesity-induced inflammation and thermogenesis." (PMID 34576181, 2021). "Obesity status (normal weight or obese) modified the association between DEX-induced CD4+ T-lymphocyte FKBP51 expression for both ATAQ score (p-interaction = 0.05) and ACT score (p-interaction = 0.07) but not for outcomes of ASUI score and FEV1pp." (PMID 34721414, 2021).
Obesity (continued). "Our analysis shows that maternal obesity leads to increased accumulation of effect or memory UCB CD4 T cells that was associated with increased methylation of loci associated with “naïve” T cell identity in samples from babies born to mothers with obesity." (PMID 33912153, 2021). "Our results suggest that immunotherapy resistance in the context of host obesity is caused by blunted effector CD4+ and CD8+ T cell responses." (PMID 34064933, 2021). "The current study addresses the specific role of CD4+ T cells in obesity-associated low type-2 asthma." (PMID 34576307, 2021). "Consistent with patient data where obesity has been linked to a higher total lymphocyte count, the obese mice had higher levels of CD4+ T cells before tumour engraftment compared to lean mice, while the level of CD8+ T cells was similar in both mouse types." (PMID 34445503, 2021). "Obesity is known to be associated with immune dysfunction, characterized by increased T-cell numbers and a shift in CD4+ T cell subsets toward a pro-inflammatory phenotype." (PMID 33670988, 2021). "In this study, we show that obesity is associated with increased CD4+ T cell proliferation and IL-17A production in PLWH." (PMID 35111163, 2021). "Among diverse subsets of CD4+ cells, activation of T helper 1 (Th1) and T helper 17 (Th17) subsets has been implicated in obesity-induced adipose inflammation." (PMID 34445379, 2021). "Transient CD3 depletion also restores the TH1/Treg balance and reverses HFD-induced insulin resistance, suggesting an upstream role for CD4+ T cell in controlling obesity-associated metabolic abnormalities." (PMID 32581740, 2020). "As well, both obesity and aging are associated with a marked increase in the CD4/CD8 T cell ratio and higher T cell IFNγ production in response to anti-CD3 plus anti-CD28 stimulation." (PMID 32027700, 2020). "The increase in the CD8+ to CD4+ T cell ratio observed in HIV infection is like that seen in diet-induced obesity, though the mechanisms underlying the accumulation of CD8+ T cells in the adipose tissue of PLWH are not well-defined." (PMID 30941121, 2019). "We also attempt to highlight the therapeutic potentials of targeting CD4+ T cells to treat obesity and its associated metabolic syndrome." (PMID 30233575, 2018). "By contrast, reconstitution with STAT6−/− CD4+ T cells leads to the loss of the insulin-sensitizing effects of the WT CD4+ T cells, suggesting that Th2 cells are important controllers of obesity and insulin resistance." (PMID 30233575, 2018). "Adoptive transfer of CD4+ T cells into HFD-fed Rag1-null mice has normalized obesity-associated insulin resistance." (PMID 30233575, 2018). "CD4+ T cells are involved in the inflammatory feedback loop in obesity-associated tissue inflammation." (PMID 28651594, 2017). "Our simulation results recovered altered stabilities of different CD4+ T cells in a way that is qualitatively similar to the alterations reported for CD4+ T cell populations in murine models and humans during obesity-associated chronic inflammation." (PMID 28651594, 2017). "The model also provides an explanation to some apparently paradoxical behaviors observed in CD4+ T regulatory cell populations during obesity-associated chronic inflammation." (PMID 28651594, 2017). "The model presented here combines the regulatory network that underlies CD4+ T cell attainment with the effect of hyperinsulinemia to provide a mechanistic explanation to the dynamical behavior of CD4+ T cells during obesity-associated chronic inflammation." (PMID 28651594, 2017). "Obesity is frequently linked to insulin resistance, high insulin levels, chronic inflammation, and alterations in the behaviour of CD4+ T cells." (PMID 28651594, 2017). "Taken together, the data suggest that obesity-associated inflammation attracts dendritic cells, which then present antigen to CD4+ T cells." (PMID 26146464, 2015).
Obesity (continued). "Circulating CD4+ T cell frequency consistently correlates positively with increased BMI or adiposity in human subjects, making them likely players in obesity-associated metabolic dysfunction." (PMID 26146464, 2015). "CD4+ T cells also play a pivotal role in the progression of obesity and are associated with inflammation via cytokine secretion." (PMID 23576853, 2013). "The widespread decrease in Treg percentages and numbers in obesity indicates that loss of Tregs likely reinforces the expansion of the inflammatory CD4+ T cell subsets that play vital roles in obesity-associated IR2,7." (PMID 26366435, 2013). "We conclude that GSPE diverted differentiation of CD4+ T cells toward a Treg phenotype in murine model of obesity-associated autoimmune arthritis through a modulation of STAT3 proteins." (PMID 24223854, 2013). "Factors positively associated with the risk of being overweight/obesity included being married (adjusted incidence rate ratio [aIRR] 2.34; 95% CI 1.24, 4.40), lower baseline CD4 count (aIRR 4.13; 95% CI 1.41, 13.38) and higher waist circumference (WC) values (aIRR 1.07; 95% CI 1.03, 1.11)." (PMID 40920752, 2025). "Moreover, obesity is negatively associated with the maintenance of vaccine‐specific CD4+ T cell memory in people with T2D." (PMID 41367201, 2025). "We also observed that CD4 cell count was substantially linked with overweight and obesity." (PMID 39735593, 2024). "Studies have shown that CD4(+) T lymphocytes in visceral adipose tissue (VAT) control the progression of metabolic abnormalities associated with obesity, including expansion of adiposity and pathogenic VAT T cells, which can be successfully reversed by immunotherapy." (PMID 37056675, 2023). "Furthermore, HFD-induced obesity has been reported to be associated with chronic inflammation within adipose tissue caused by accumulation of CD4+ and CD8+ T cells." (PMID 37929799, 2023). "Furthermore, IPA analysis indicated that CD4+ T cells expressed high levels of the downstream genes of the key inflammatory pathways associated with obesity." (PMID 36880999, 2023). "We then assessed other T cell subsets associated with obesity and aging; notably CD4+ Tregs." (PMID 36776393, 2022). "VAT CD4 T cells play an important role in regulating inflammation and metabolism in obesity, but the underlying mechanisms are largely unknown." (PMID 36685567, 2022). "In addition to causing T-cell exhaustion, obesity also accelerates cellular senescence of CD4 T cells." (PMID 36685567, 2022). "However, adoptive transfer of Tregs in CD4+ T cell-specific KLF10 deficient mice impede obesity, IR, adipose tissue inflammation and fatty liver phenotype." (PMID 35912096, 2022). "We next asked if dampened UCB CD4 T cell responses with maternal obesity could be linked to shifts in inflammatory cytokine milieu and metabolic hormones in cord blood plasma." (PMID 33912153, 2021). "Obesity is associated with an impaired balance of CD4+ T cell subsets." (PMID 33670988, 2021). "Increasing evidence supports a pathogenic function for CD4+ T cells in obesity and IR." (PMID 34557550, 2021). "However, host obesity is associated with heightened immunotherapy resistance, characterized by multi-factorial deficiencies in effector CD4+ and CD8+ T cell responses that extend beyond the tumor microenvironment." (PMID 34064933, 2021). "Now, in the combination ART era, a BMI ≥ 30 kg/m2 at treatment initiation is associated with greater CD4+ T cell reconstitution, suggesting that obesity in PLWH initiating ART may potentially play a protective role in immune reconstitution." (PMID 35111163, 2021). "In addition, hepatitis B surface antigen-specific CD4+ T cells showed significantly less proliferation in PBMCs of high-risk obesity NAFLD patients compared to that in low-risk obesity NAFLD subjects." (PMID 34869507, 2021).